RNU6-1204P (RNA, U6 small nuclear 1204, pseudogene)
Gene: Small nuclear RNA gene on chromosome 14 (56,824,986 to 56,825,092, forward strand). Ensembl gene ENSG00000200818.
Homologues: Orthologues: chimpanzee U6 (98% identical), macaque U6 (89% identical), pig U6 (79% identical), dog U6 (76% identical), guinea pig U6 (61% identical). Paralogues in human: RNU6-16P (85% identical), RNU6-38P (85% identical), RNU6-144P (84% identical), RNU6-20P (84% identical), RNU6-393P (84% identical), RNU6-434P (84% identical), RNU6-812P (84% identical), RNU6-1035P (83% identical), RNU6-1145P (83% identical), RNU6-25P (83% identical), RNU6-29P (83% identical), RNU6-468P (83% identical), and 1290 more.